PPP2R2A (protein phosphatase 2 regulatory subunit Balpha)
Diseases named in the same sentence as PPP2R2A in open-access papers (continued):
Sharing a sentence is not in itself a finding about the gene and the disease.
bladder cancer (4 papers, 2016 to 2025). "Together, these results indicated that PPP2R2A was a direct target of miR‐222 in bladder cancer cells in a manner associated with miR‐222‐induced proliferation." (PMID 26800397, 2016). "In bladder cancer, miR-222 attenuated cisplatin-induced cell death by targeting the PPP2R2A/Akt/mTOR axis." (PMID 39951446, 2025). "miR‐222 activated the Akt/mTOR pathway and inhibited cisplatin‐induced autophagy in bladder cancer cells by directly targeting protein phosphatase 2A subunit B (PPP2R2A)." (PMID 26800397, 2016). "To explore the role of PPP2R2A in the miR‐222‐induced proliferation of bladder cancer cells, we constructed the pcDNA3.1‐PPP2R2A plasmid to rescue the decreased level of PPP2R2A induced by miR‐222 overexpression." (PMID 26800397, 2016). "Overexpression of miR‐222 in vitro down‐regulated the expression of PPP2R2A in bladder cancer cells." (PMID 26800397, 2016). "Importantly, our study highlighted for the first time a novel miR‐222/PPP2R2A/Akt/mTOR axis that regulates CDDP sensitivity in bladder cancer." (PMID 26800397, 2016). "To analyse whether the PPP2R2A/Akt axis played an important role in miR‐222‐mediated proliferation of bladder cancer cells, we used the specific PI3K inhibitor LY294002 to suppress Akt phosphorylation." (PMID 26800397, 2016). "Our findings revealed that PPP2R2A is a direct target of miR‐222 in bladder cancer cells." (PMID 26800397, 2016). "Therefore, our data demonstrated that the PPP2R2A/Akt/mTOR axis played a regulatory role in the miR‐222‐induced proliferation of bladder cancer." (PMID 26800397, 2016). "Interestingly, PPP2R2A is a known target of miR-221 in hepatocellular and bladder cancer cells." (PMID 31221814, 2019). "PPP2R2A is a negative regulator of ATM-CHK2 and a candidate tumor suppressor gene commonly deleted in ovarian, prostate, liver, and bladder cancers." (PMID 33788831, 2021). "Together, these data demonstrate that the PPP2R2A/Akt/mTOR axis is required for miR‐222‐mediated proliferation and CDDP‐induced cell death in bladder cancer cells." (PMID 26800397, 2016). "The PPP2R2A/Akt/mTOR axis was required for miR‐222‐induced proliferation and CDDP resistance in bladder cancer cells." (PMID 26800397, 2016). "In the present study, we found that miR‐222 promoted the proliferation of bladder cancer cells and attenuated CDDP‐induced cell death by regulating the PPP2R2A/Akt/mTOR axis, which indicated that miR‐222 might be a novel therapeutic target for bladder cancer." (PMID 26800397, 2016).
hepatocellular carcinoma (4 papers, 2016 to 2021). A malignant tumor that arises from hepatocytes. "In hepatocellular carcinoma cells, miR‐222‐induced down‐regulation of PPP2R2A is associated with Akt activation." (PMID 26800397, 2016). "PPP2R2A is a known target of miR‐222 in hepatocellular cancer cells." (PMID 26800397, 2016).
osteosarcoma (4 papers, 2019 to 2024). A usually aggressive malignant bone-forming mesenchymal neoplasm, predominantly affecting adolescents and young adults. "MiR-221 is responsible for cisplatin resistance in osteosarcoma cells through protein phosphatase 2 regulatory subunit B alpha (PPP2R2A) downregulation." (PMID 34199293, 2021). "Interestingly, PPP2R2A downregulation is also involved in microRNA-221-mediated cisplatin resistance in osteosarcoma cells, linking PPP2R2A low expression to cisplatin resistance." (PMID 39659585, 2024).
atherosclerosis (3 papers, 2015 to 2022). A disease characterized by the build-up of fatty material and calcium deposition in the arterial wall resulting in partial or complete occlusion of the arterial lumen. "The up-modulation of abnormal miR-136-5p in atherosclerosis promotes the proliferation of abnormal vascular smooth muscle cells via the ERK1/2 signaling pathway by targeting PPP2R2A." (PMID 35236239, 2022). "miR-136 promotes vascular muscle cell proliferation through the erk1/2 pathway by targeting ppp2r2a in atherosclerosis." (PMID 33024632, 2020).
colon cancer (3 papers, 2014 to 2023). "PPP2R2A acts as a tumor suppressor gene, and suppression of PPP2R2A increases the proliferation of leukemia cells and human colon cancer cells." (PMID 38028209, 2023).
gastric cancer (3 papers, 2021 to 2023). A primary or metastatic malignant neoplasm involving the stomach. "Studies have found that PPP2R2A suppresses gastric cancer cell proliferation, invasion, and epithelial-mesenchymal transition (EMT)." (PMID 36803971, 2023). "MiR-665 has been demonstrated to exert anti-proliferation effect in gastric cancer via targeting PPP2R2A." (PMID 35322746, 2022). "But, miR-665 was reported to promote PPP2R2A overexpression and inhibit the proliferation and epithelial–mesenchymal transition of gastric cancer cells." (PMID 33588847, 2021).
papillary thyroid cancer (3 papers, 2021 to 2024). "For example, MiR-222 can suppress PPP2R2A expression and promote the proliferation or invasion of papillary thyroid cancer, diffuse large B-cell lymphoma and HCC." (PMID 33588847, 2021).
prostate tumors (3 papers, 2019 to 2020). "Consistent with the possibility that complete loss of PPP2R2A is detrimental in prostate tumors, PPP2R2A deletion in cells with reduced but present B55α reduces cell proliferation by slowing progression through the cell cycle." (PMID 31822657, 2019). "Analysis of 492 prostate tumor genomes from the TCGA dataset indicated that hemizygous loss of PPP2R2A occurred in ~42% (206/492) of prostate adenocarcinomas (shallow deletion)." (PMID 31822657, 2019). "Somatic deletions were also observed in 67% prostate tumor samples and deletions encompassing B55α and B55β genes PPP2R2A and PPP2R2B were found in primary plasma cell leukemia and in multiple myeloma patients, respectively." (PMID 33266510, 2020). "Hemizygous loss of PPP2R2A was associated with reduced B55α mRNA expression (p-value 6.68 × 10−11), but not reduced expression of a known prostate tumor suppressor NKX3-1 (p-value 0.74), which is also located on Chr." (PMID 31822657, 2019).
thyroid cancer (3 papers, 2021 to 2024). "In vitro studies revealed that miR-222 exerts its effects via 3′-UTR of protein phosphatase 2 regulatory subunit B alpha (PPP2R2A), thus enhancing the invasiveness and the migration of thyroid cancer cells." (PMID 34199293, 2021).
acute leukemia (2 papers, 2020 to 2024). A clonal (malignant) hematopoietic disorder with an acute onset, affecting the bone marrow and the peripheral blood. "Loss of function mutations on the PPP2R2A gene were additionally observed in acute leukemia blasts and were associated with the disappearance of B55α expression." (PMID 33266510, 2020).
diabetes (2 papers, 2015 to 2024). "Mutations in the PPP2R2A gene have been associated with diabetes and insulin resistance, participating in the regulation of glucose metabolism." (PMID 38601640, 2024).
HIV-1 infection (2 papers, 2018 to 2023). The type species of lentivirus and the etiologic agent of acquired immunodeficiency syndrome (AIDS). "RTEL1 is linked to pulmonary fibrosis, TRIM34 plays a role in restricting HIV-1 infection, PPP2R2A is a potential therapeutic target, and IRF7 shows high expression in certain COVID-19 patients, underlining the diverse implications of these genes in the context of SARS-CoV-2 infection." (PMID 38681774, 2023).
leukemia (2 papers, 2016 to 2023). A malignant (clonal) hematologic disorder, involving hematopoietic stem cells and characterized by the presence of primitive or atypical myeloid or lymphoid cells in the bone marrow and the blood. "Although mutations in the PPP2R2A gene have been reported to occur as frequently as 15% in several types of solid tumors, no prior studies have provided a conclusive mechanism for alterations in B55α expression levels in leukemia." (PMID 27531894, 2016).
lupus (2 papers, 2025). "GEF–H1 exemplifies functional pleiotropy in immune dysregulation: In systemic lupus erythematosus (SLE), PPP2R2A‐mediated dephosphorylation of GEF–H1 activates the RhoA–ROCK axis, driving pathogenic IL‐17/IFN‐γ production in T cells." (PMID 41020039, 2025). "T-cell-specific deletion of PPP2R2A reduced TH17 cell numbers and autoimmune syndrome development in an EAE model and lupus-prone mice." (PMID 39944077, 2025).
melanoma (2 papers, 2019 to 2021). A malignant, usually aggressive tumor composed of atypical, neoplastic melanocytes. "Next, we examined the effects of DUSP4 and PPP2R2A depletion in two additional melanoma cell lines, both harboring BRAF mutations." (PMID 32767816, 2021). "We verified that genetic inactivation of DUSP4 and PPP2R2A reduces the proliferation of melanoma cells." (PMID 32767816, 2021). "We verified the fitness effects of DUSP4 and PPP2R2A in multiple melanoma cell lines." (PMID 32767816, 2021). "In vitro experiments in human melanoma cell lines confirmed that inactivation of DUSP4 and PPP2R2A results in decreased cell proliferation." (PMID 32767816, 2021). "In support of a key role for PP2A in regulating BRAF activity, we found that in melanoma cells, depletion of PPP2CA or PPP2R2A led to increased p-S365-BRAF and decreased MEK/ERK activity." (PMID 31015455, 2019). "More importantly, TNFα failed to activate BRAF in PPP2R2A-depleted melanoma cells." (PMID 31015455, 2019). "DUSP4 and PPP2R2A were homogenously expressed among the 28 melanoma cell lines and transcript levels did not provide an explanation for the difference in sensitivity to inactivation—this might imply post‐translational factor influence on the function of these genes." (PMID 32767816, 2021).
esophageal cancer (1 paper, 2014). A primary or metastatic malignant neoplasm involving the esophagus. "For example, miR-31 is upregulated in esophageal cancer and promotes cancer development via suppression of its target gene, PPP2R2A." (PMID 25202407, 2014).
folate deficiency (1 paper, 2018). A nutritional condition produced by a deficiency of FOLIC ACID in the diet. "Folate deficiency-induced tau hyperphosphorylation can be attenuated by PPP2R2A overexpression." (PMID 29950985, 2018).
heart failure (1 paper, 2024). Inability of the heart to pump blood at an adequate rate to meet tissue metabolic requirements. "TMEM87A, PPP2R2A, DUSP1, and miR-92a have great potential as biomarkers for heart failure." (PMID 38886500, 2024).
Hyperkeratosis (1 paper, 2013). Hyperkeratosis is a histopathological term defining a thickened stratum corneum and may be present in many different skin conditions, with many possible overlaps. "This treatment was also sufficient to reduce hyperkeratosis in the Ppp2r2a siRNA kd organotypic cultures." (PMID 23685254, 2013). "Barrier function was restored in the Ppp2r2a kd cultures concomitant with hyperkeratosis." (PMID 23685254, 2013).
metastatic disease (1 paper, 2019). "Homozygous loss (deep deletion) of PPP2R2A in prostate adenocarcinomas was less common (15%; TCGA), particularly in datasets reporting metastatic tumors (<5%; SU2C)." (PMID 31822657, 2019). "Here, we report that PPP2R2A is hemizygously lost in ~42% of prostate adenocarcinomas, correlating with reduced expression, poorer prognosis, and an increased incidence of hemizygous loss (>75%) in metastatic disease." (PMID 31822657, 2019).
prostate adenocarcinoma (1 paper, 2019). "This is consistent with the DFS calculated in an independent cohort with hemizygous loss of PPP2R2A (the MSKCC prostate adenocarcinoma data set, 194 tumors, p-value of 0.0053, Suppl." (PMID 31822657, 2019). "Importantly, hemizygous loss of PPP2R2A expression correlated with poorer prognosis, based on Kaplan-Meier estimates of disease-free survival (DFS) using TCGA data from patients with prostate adenocarcinoma (p-value 0.0466)." (PMID 31822657, 2019).
tongue cancer (1 paper, 2017). A malignant neoplasm affecting the tongue. "In Zinc deficiency esophagus and tongue cancers, oncogenic miR-31 overexpression was accompanied by down-regulation of their respective tumor-suppressor targets PPP2R2A and PDCD4." (PMID 29145896, 2017).
Zinc deficiency (1 paper, 2025). A deficiency of the essential metal Zinc; an essential cofactor for many enzymes. "Studies have found that zinc deficiency increased pro-inflammatory and oncogenic miRNAs such as miR-21, miR-31, and miR-146a in esophagus and tongue tissues by suppressing tumor suppressor genes PDCD4 and PPP2R2A." (PMID 41228448, 2025).
tumor (49 papers, 2010 to 2025). "Low expression of PPP2R2A in gastric cancer tissues is associated with tumor staging, lymph node metastasis, and poor prognosis." (PMID 37894282, 2023). "PR55α (encoded by PPP2R2A) can function as both an oncogene and tumor suppressor in different cancers." (PMID 33588847, 2021). "Several lines of data suggest that reduced expression of PPP2R2A, the gene encoding the B regulatory subunit B55α, promotes tumor pathogenesis." (PMID 31822657, 2019). "In the case of our patient samples with PPP2R2A gene mutation, this tumor suppressive function of PP2A is lost and aberrant AKT signaling is present." (PMID 27531894, 2016). "Interestingly, all these novel peptide sequences map to 5′UTR except PPP2R2A, and the parent genes of many of them are associated with multiple (more than four) hallmarks of cancer implicating their determinant role in tumor pathogenesis." (PMID 35227895, 2022). "Animals harboring xenograft tumors derived from PPP2R2A stable KD cells exhibited a substantial reduction in tumor size upon CHK1i treatment, resulting in a marked inhibition of tumor growth." (PMID 39659585, 2024). "The combination group exhibited significantly smaller tumor volume and weight compared to the group with PPP2R2A KD alone at the end of treatment." (PMID 39659585, 2024). "Since this study demonstrated that VPA was able to regulate PPP2R2A function in both tumor and normal cells, so it would be necessary to further distinguish if VPA plays a role on PPP2R2A at the transcription or post-transcription level." (PMID 36781846, 2023). "In summary, we demonstrated that VPA exerts bidirectionally effect on regulating cell cycle progression through PPP2R2A (D197 and N181)-Chk1 signaling axis in tumor and normal cells." (PMID 36781846, 2023). "We confirmed that nuclear lamins are increasingly dephosphorylated (detected with Lamin‐A/C phospho‐antibody) upon PME‐1 depletion and that this effect is dependent on the PP2A complex B‐subunit PPP2R2A, an established tumour suppressor in PCa." (PMID 36461911, 2023). "Here, we report that VPA has a bidirectional effect on the tumor and normal cell survival through selective regulation of cell cycle progression through the PPP2R2A-Chk1 pathway." (PMID 36781846, 2023). "In fact, PPP2R2A refers to a large family of heterotrimeric Ser/Thr phosphatases and can be considered a tumor suppressor gene that regulates tumor growth." (PMID 36803971, 2023). "DAPK1 is a serine/threonine kinase, a tumor suppressor protein that promotes apoptosis, while PPP2R2A, a regulatory subunit of protein phosphatase 2A (PP2A), controls the pathway of AKT signaling associated with tumor growth." (PMID 34305611, 2021). "Here, we first used public data from large cohorts of PCa patients to establish evidence for PPP2R2A as a haploinsufficient tumor suppressor." (PMID 31822657, 2019). "As a tumor suppressor gene, PPP2R2A is reported to be involved in cancer cell proliferation and migration." (PMID 31221814, 2019). "To establish the mechanistic basis of PPP2R2A tumor suppressor activity in PCa, we first tried to develop stable overexpression cell lines for B55α in PC3 and DU145 cells." (PMID 31822657, 2019). "PPP2R2A, also known as protein phosphatase 2A B55 subunit, has been demonstrated as a tumor suppressor that induces apoptosis." (PMID 28783765, 2017). "Numerous genes known to be highly expressed in proliferating cells (Tfrc, metallothioneins genes) were upregulated by the HPD while tumor suppressor genes (Ppp2r2a, Ndrg1 and Prdx1) were downregulated by the HPD (q < 0.01)." (PMID 28137254, 2017). "Nodal disease values were imputed adjusting for tumor size, the PPP2R2A (B55α)/Cyclin D1 phenotype and HER2 status." (PMID 25879784, 2015). "Taken together, these findings lead to the conclusion that PP2A, as well as some of its regulatory subunits, such as PPP2R2A, have definitive roles as tumor suppressors in a large variety of cancers." (PMID 25879784, 2015).